BMI1 (BMI1 proto-oncogene, polycomb ring finger)
Diseases named in the same sentence as BMI1 in open-access papers (continued):
Sharing a sentence is not in itself a finding about the gene and the disease.
non-small cell lung carcinoma (25 papers, 2001 to 2025). A group of at least three distinct histological types of lung cancer, including non-small cell squamous cell carcinoma, adenocarcinoma, and large cell carcinoma. "It was the aim of this study to assess the expression of bmi-1 in resectable non-small cell lung cancer (NSCLC) in association with p16 and p14ARF (=human p19ARF)." (PMID 11355949, 2001). "In non-small cell lung cancer, the BMI1/MALAT1 axis sequesters miR-145-5p to support tumor survival." (PMID 40623983, 2025). "A meta-analysis of non-small cell lung cancer revealed a correlation between elevated Bmi-1 expression and increased tumor size, metastasis, and lower overall survival rates." (PMID 36726797, 2023). "For instance, in non-small cell lung cancer, BMI1 is required for K-Ras induced tumorigenesis in vivo and plays its tumorigenic role by repressing the INK4b-ARF-INK4a locus." (PMID 33804165, 2021). "Independent validations on NUMA1-proficient HAP1 and non-small cell lung cancer cell lines exposed to BMI1 inhibition by PTC-318 or BMI1 knockdown resulted in cell death following mitotic arrest." (PMID 32343689, 2020). "Recent studies have found a positive correlation between Bmi-1 levels and survival and recurrence in patients with tongue cancer, squamous cell carcinoma of the oropharynx, and non-small cell lung cancer." (PMID 26317630, 2015). "BMI-1 is also indispensable for the regulation of self-renewal in non-small cell lung cancer." (PMID 29299167, 2017). "Deguelin induces apoptosis in non-small cell lung cancer cells, for example, by repressing Noxa through B lymphoma Mo-MLV insertion region 1 homolog (BMI1) regulation." (PMID 30405048, 2018). "For example, in a non-small-cell lung cancer (NSCLC) model, isolated CSCs exhibited elevated FOXM1, the knockdown of which resulted in reduced expression of stem cell markers (CD133 and CD44), stem cell regulators (Bmi1, Sox2, and Oct4), and self-renewal." (PMID 37174744, 2023). "Additionally, almost all murine GBM CTCs expressed Olig2, and 40% expressed CD133; CSC markers are detected on a fraction of CTCs in a variety of types of cancer, including breast cancer (CD44), colorectal cancer (LGR5), non-small cell lung cancer (NSCLC) and ovarian cancer (BMI1, CD133, ALDH1)." (PMID 38609981, 2024).
osteosarcoma (21 papers, 2009 to 2025). A usually aggressive malignant bone-forming mesenchymal neoplasm, predominantly affecting adolescents and young adults. "BMI-1 is a member of the polycomb group of genes (PcGs), and it has been implicated in the development and progression of several malignancies, but its role in osteosarcoma remains to be elucidated." (PMID 21311599, 2011). "Elevated levels of Bmi-1 protein have been detected in various cancer types, including osteosarcoma." (PMID 38141761, 2024). "We noted that BMI1 is robustly expressed in pediatric sarcomas, such as Ewing sarcoma and osteosarcoma, as well as in adult subtypes, including leiomyosarcoma and chondrosarcoma." (PMID 33523558, 2021). "Mechanistic analysis indicated that circRNA-0008717 suppressed the capacity of proliferation, migration and invasion of osteosarcoma cells through specifically sponging miR-203 and releasing Bmi-1." (PMID 29854278, 2018). "To further test the functional importance of the BMI1 UBL domain interactions we performed clonogenic survival assays in the human osteosarcoma U2OS cell line." (PMID 27827373, 2016). "We report positive BMI1 expression in 82% (14/17) human osteosarcoma samples analyzed, which is higher than the 56% reported previously." (PMID 26110620, 2015). "Although BMI-1 has been implicated as an oncogenic player, very little is known about the exact function of BMI-1 in osteosarcoma growth and progression." (PMID 21311599, 2011). "As elevated BMI-1 expression was found in several types of human cancers, we first determine the expression of BMI-1 protein in osteosarcoma through immunohistochemical analysis." (PMID 21311599, 2011). "In contrast, positive expression of BMI-1 was observed 18/32 in osteosarcoma, 9/22 in chondrosarcoma, 3/9 in Ewing's sarcoma and 5/27 in osteochondroma (a benign neoplasm)." (PMID 21311599, 2011). "Downregulation of BMI-1 by lentivirus mediated RNA interference (RNAi) significantly impaired cell viability and colony formation in vitro and tumorigenesis in vivo of osteosarcoma cells." (PMID 21311599, 2011). "Our findings confirm that BMI-1 is highly expressed in osteosarcoma cells, and it promotes tumor growth in vitro and in vivo." (PMID 21311599, 2011). "In the present study, we found that BMI-1 was highly expressed in malignant osteosarcoma, and it is essential for cancer cell proliferation, migration and in vivo tumorigenicity." (PMID 21311599, 2011). "We subsequently explore the possible molecular mechanism by which BMI-1 protected osteosarcoma cells from cisplatin induced apoptosis." (PMID 21311599, 2011). "We demonstrated for the first time that the knockdown of endogenous BMI-1 expression contributed to sensitizing osteosarcoma cells to the anticancer drug cisplatin by increasing apoptosis." (PMID 21311599, 2011). "In summary, our results demonstrated that BMI-1 functions as an oncogene in osteosarcoma and that it promotes tumorigenicity and resistance to chemotherapy." (PMID 21311599, 2011). "Indeed, BMI1 expression was found to be upregulated in both human and canine osteosarcoma cell lines, and its inhibition in vitro significantly reduced cell proliferation and increased sensitivity to carboplatin and doxorubicin in different canine lines." (PMID 40563676, 2025). "The overall results highlighted an interesting translational comparability between the tumor biology of human and canine osteosarcoma and a potential utility of targeting BMI1 in CSCs of this malignancy to overcome the challenge of DR in response to first-line chemotherapeutics." (PMID 40563676, 2025). "Finally, our gain and loss-functional assays verified that circRNA-0008717 promotes osteosarcoma progression by sponge activity of miR-203 and upregulation of Bmi-1 expression." (PMID 29854278, 2018).
osteosarcoma (continued). "To further identify whether Bmi-1 in osteosarcoma cells responded to miR-203 through direct interactions with its 3′-UTR, we cloned the wild type 3′-UTR of the putative miR-203 target or mutant sequences into reporter plasmid downstream of the luciferase gene." (PMID 29854278, 2018). "Bmi-1 was upregulated in osteosarcoma cells by Bmi-1 overexpression vector." (PMID 29854278, 2018). "This suggests that miR-203 suppresses osteosarcoma progression through targeting Bmi-1." (PMID 29854278, 2018). "Interestingly, a recent report demonstrated that BMI-1 functioned as an oncogene in osteosarcoma and overexpression of BMI-1 promoted cell growth and resistance to cisplatin treatment in osteosarcoma through PI3K/AKT pathway." (PMID 23372675, 2013). "Furthermore, our data show that BMI-1 also play an important role in osteosarcoma cell migration and chemosensitivity to cisplatin-induced apoptosis." (PMID 21311599, 2011). "Measurement of caspase-3 and caspase-9 activities further confirmed that silencing BMI-1 expression could enhance cisplatin-induced apoptosis, further explaining clearly the signaling pathway of cisplatin-induced apoptosis in osteosarcoma." (PMID 21311599, 2011). "In the present study, we found that BMI-1 was overexpressed in different types of osteosarcomas." (PMID 21311599, 2011). "We also examined the role of BMI-1 in osteosarcoma cell migration." (PMID 21311599, 2011). "Our findings suggest that the combination of cisplatin treatment and BMI-1 depletion could be a therapeutic strategy for osteosarcoma." (PMID 21311599, 2011). "In addition, overexpression of circRNA-0008717 in osteosarcoma could elevate Bmi-1 expression, resulting in the promotion of osteosarcoma cell proliferation and invasion." (PMID 29854278, 2018). "Given that BMI-1 is upregulated in most stem cells and its expression is vital for the self-renewal of normal and tumorigenic stem cells, it is possible that the high level of BMI-1 expression we observed in osteosarcoma cells is an inherent feature of their cellular origin." (PMID 21311599, 2011). "In this study we have investigated whether BMI-1 functions as an oncogene in osteosarcoma." (PMID 21311599, 2011). "Meanwhile, osteosarcoma cells with overexpressed TBL1XR1 had higher expression of stemness markers including ABCG2, BMI1, SOX2, NANOG, and OCT4, indicating that TBL1XR1 endowed osteosarcoma cells with stem cell-like properties." (PMID 38347836, 2024). "Through BMI1 and ZEB2, ZFAS1 regulates osteosarcoma cell growth and metastasis." (PMID 35184675, 2022). "Similarly, the B-cell-specific Moloney murine leukemia virus integration site 1 (BMI1), a member of the Polycomb repressive complex 1 (PRC1) of transcriptional regulators, has been found to be highly expressed in tissue samples of primary and metastatic osteosarcoma from both dogs and humans." (PMID 40563676, 2025).
breast tumors (20 papers, 2007 to 2024). "Elevated SLUG expression in breast tumors induces overexpression of stem-like genes, such as BMI1 and CD133." (PMID 38555451, 2024). "Oncogenic FAL1 binds and stabilizes epigenetic repressor BMI1, resulting in suppression of gene transcription, and then to malignant transformation and breast tumor growth." (PMID 28558830, 2017). "For proof of the concept, we have used molecular approaches to illustrate the impact of Bmi1 downregulation on breast CSC in a novel model of mouse immunocompetent breast CSC-driven breast tumor generation." (PMID 28418883, 2017). "Immunohistochemical analysis was performed on 25 breast tumor tissue sections to determine the expression of Bmi1 at protein level." (PMID 25348805, 2014). "Our observation that Bmi1 and Nanog are co-expressed in breast tumors, and importantly that Bmi1 positively regulated Nanog expression, at least in part, by activating NFκB pathway helps in connecting the missing link." (PMID 25348805, 2014). "In various primary breast tumors analyzed by RT-PCR, we found that the tumors with higher Bmi1 also showed elevated Nanog and the tumors with lower Bmi1 showed reduced Nanog expression." (PMID 25348805, 2014). "The relationship between NRP2 and BMI-1 was further confirmed using NRP2high and NRP2low sorted populations from freshly isolated breast tumours." (PMID 23436775, 2013). "Additionally, we showed that USP2 expression is positively correlated with Twist and Bmi1 expression in breast tumor specimens." (PMID 30918246, 2019). "Furthermore, treatment of hinokitiol in vivo suppressed the growth of xenograft human breast tumors as well as the expression of BMI1 and ALDH1A1 in xenograft tumors." (PMID 29100291, 2017). "To conclude, our study showed that Bmi1 is upregulated in primary breast tumors." (PMID 25348805, 2014). "Similarly, GLI1 increased BMI-1 expression in the NRP2low population of cells isolated from human breast tumours." (PMID 23436775, 2013). "Therefore, we stained normal mammary gland tissue as well as breast tumour material for both BMI1 and EZH2 protein expression." (PMID 19099573, 2008). "Our results from the correlative analysis suggested that the presence of Bmi-1 mRNA in plasma of patients with breast tumors may be a possible prognostic marker, which can be obtained by a noninvasive method." (PMID 17711569, 2007). "In addition, miRNA-128 was significantly reduced in chemoresistant breast tumor-initiating cells (BT-ICs) enriched from breast cancer cell lines and primary breast tumors (P < 0.01), accompanied by an overexpression of Bmi-1 and ABCC5, which were identified as targets of miRNA-128." (PMID 24555688, 2014). "We conclude that transduction of normal HMECs with lentiviruses expressing ERα, BMI1, MYC and TERT confers the ability to form metastatic ERα-positive breast tumours." (PMID 17573968, 2007). "As for MCF-7, our results are in line with Sox2 and Bmi1 transcripts, but not nuclear ERα, being increased in Col-I-enriched ER+ murine breast tumors." (PMID 32435546, 2020). "In the SQ breast tumors, we observed significantly upregulated mRNA levels of the Oct3/4 regulatory network, including ONSS, and several other PTFs, including Nanog, Sall4, Sox2, Sox4, FoxA2, Gata6, Zic2 and HoxB7, as well as Oct3/4 isoform B, polycomb suppressors Bmi1, EzH2, Amigo and Dkk1." (PMID 37298091, 2023).
head and neck cancer (19 papers, 2011 to 2025). A primary or metastatic malignant neoplasm affecting the head and neck. "The function of Bmi-1 in head and neck cancers to promote metastasis has been associated with the activity in regulating the epithelial-mesenchymal transition (EMT) process." (PMID 39866230, 2025). "This review focuses on Bmi-1’s involvement in head and neck cancer, a condition for which it is assumed to be a promising target for implementing innovative therapeutic interventions." (PMID 39866230, 2025). "Unraveling the Bmi-1’s precise functional role in head and neck cancers can be attractive for mechanisms-based developmental therapeutics." (PMID 39866230, 2025). "This review attempts to synthesize the current knowledge on Bmi-1 with an emphasis on the role that Bmi-1 plays in oral cancer progression and evaluates how this can be used in advancing clinical treatment strategies for head and neck cancer." (PMID 39866230, 2025). "In this review, we discuss the parallels in the role of Bmi-1 in stem cell biology of health and disease and explore how this can be leveraged to advance clinical treatment strategies for head and neck cancer." (PMID 36726797, 2023). "While there are limited published studies on the efficacy of Bmi-1 inhibitors in head and neck cancers, the success of these small molecule drugs in treatment of other cancers in preclinical and clinical models strongly supports their therapeutic potential." (PMID 36726797, 2023). "In head and neck cancer, Bmi-1 is more highly expressed in tumorigenic cells as compared to normal cells." (PMID 36726797, 2023). "In this review, we specifically elaborate on the role and molecular regulatory network of Bmi-1 in mediating head and neck cancer stemness." (PMID 36726797, 2023). "Characterizing Bmi-1 as an oncogene is a novel, active area of research in head and neck cancer, with limited literature on the exact mechanism and signaling pathways in interplay with Bmi-1." (PMID 36726797, 2023). "We have reviewed the prominent impact Bmi-1 has on tumorigenesis, metastasis, and therapy resistance of head and neck cancers." (PMID 36726797, 2023). "Few research studies to date have robustly investigated Bmi-1 expression patterns in head and neck cancer." (PMID 36726797, 2023). "Blockade of IL-6R with a humanized monoclonal antibody (Tocilizumab; TCZ) is sufficient to inhibit Bmi-1 expression and overcome the intrinsic chemoresistance of head and neck cancer stem cells." (PMID 36091805, 2022). "Subsequently, OCT-4-induced synergistic action of ID1 and NF-κB triggers the expression of important head and neck cancer stem cell markers, BMI-1 and CD44." (PMID 33442406, 2021). "In this study, we revealed a molecular mechanism for the regulation of ERK3 expression in head and neck cancer cells: BMI1 upregulates ERK3 by suppressing let‐7i miRNA that directly targets ERK3 mRNA." (PMID 28079973, 2017). "Our finding about the tight regulation of ERK3 expression by the BMI1/let‐7i axis is important given that BMI1 is a well‐known oncoprotein and that let‐7i is a tumor suppressor in multiple cancers including head and neck cancers." (PMID 28079973, 2017). "Here, we have identified the oncogenic polycomb group protein BMI1 as a positive regulator of ERK3 level in head and neck cancer cells." (PMID 28079973, 2017). "Taken together, these results demonstrate that BMI1 positively regulates ERK3 expression in head and neck cancer cells." (PMID 28079973, 2017). "The positive regulation of ERK3 expression by BMI1 was confirmed in two other head and neck cancer cell lines, UMSCC1 and Detroit 562, in which transient knockdown of BMI1 by siRNA (siBMI1) led to a decrease in ERK3 protein level." (PMID 28079973, 2017). "We previously demonstrated that the overexpression of miR-494-3p in head and neck cancer-derived tumor initiating cells (HNC-TICs) reduces cancer stemness through the downregulation of B lymphoma Mo-MLV insertion region 1 homolog (Bmi1)." (PMID 27399693, 2016).